EZH2 (enhancer of zeste 2 polycomb repressive complex 2 subunit)
Diseases named in the same sentence as EZH2 in open-access papers (continued):
Sharing a sentence is not in itself a finding about the gene and the disease.
endometrial cancer (73 papers, 2010 to 2026). Primary or metastatic malignant neoplasm involving the endometrium (mucous membrane that lines the endometrial cavity). "EZH2, the gene which causes aberrant transcription and stemness, was also found to increase expression in type II endometrial cancer." (PMID 40433700, 2025). "The epigenetic regulator polycomb group gene EZH2, which causes aberrant transcription and enhances stemness in tumour tissue, was upregulated in type II endometrial cancer as compared to type I endometrial cancer." (PMID 40433700, 2025). "The mechanisms underlying EZH2 action in endometrial cancer progression remain incompletely understood." (PMID 35269532, 2022). "We found that the patients with endometrial carcinoma had the highest alteration frequency of EZH2 (=8%) with “mutation” as the primary type." (PMID 34381492, 2021). "For example, EZH2 overexpression in endometrial cancer causes a downregulation of the tumor suppressor gene ARID1A." (PMID 33732505, 2020). "Disrupted EZH2 expression has been implicated in several uterine diseases, including endometriosis, uterine fibroids, endometrial cancer, and other proliferative disorders." (PMID 33732505, 2020). "Kaplan-Meier survival analysis using data of the TCGA RNA-seq database and tissue microarrays (TMAs) indicated that EZH2 overexpression is associated with endometrial cancer prognosis." (PMID 28418882, 2017). "Here, we showed that EZH2 is overexpressed in endometrial cancer cells compared with that in normal cells, and high EZH2 expression is significantly associated with poor prognosis in endometrial cancer." (PMID 28418882, 2017). "Immunohistochemical analysis of the TMA specimens of endometrial cancers was performed, and high EZH2 expression was significantly associated with poor PFS (P = 0.04) but not with OS (P = 0.2175)." (PMID 28418882, 2017). "The association between expression of EZH2 and clinicopathological characteristics of 33 endometrial cancer tissues was analyzed." (PMID 25295088, 2014). "Nevertheless, EZH2 expression is associated with a high proliferation rate and aggressive tumor subgroups of endometrial cancer." (PMID 25295088, 2014). "EZH2 expression has been found to be positively associated with lipocalin 2 expression, which is associated with aggressive features of endometrial cancer." (PMID 25295088, 2014). "EZH2 expression has been linked to endometrial cancer cell invasion and metastasis." (PMID 35269532, 2022). "A critical question is whether altered EZH2 expression is in and of itself sufficient to induce uterine cancer or whether upregulation of this gene is merely associated with endometrial cancer." (PMID 33732505, 2020). "Inhibition of EZH2 expression is associated with decreased tumor cell proliferation, migration and invasion in endometrial cancer cell lines, which is parallel to an increased expression of Wnt pathway inhibitors, sFRP1 and DKK3, and a concomitant decrease in β-catenin levels." (PMID 25295088, 2014). "Moreover, the present study demonstrated that EZH2 overexpression was associated with myometrial invasion in endometrial cancer." (PMID 25295088, 2014). "In the present study, the finding that EZH2 was associated with deep myometrial invasion supports the hypothesis that EZH2 may be an important factor in the invasion of endometrial cancer cells by regulating E-cadherin, β-catenin and MMP9." (PMID 25295088, 2014). "Previous studies have demonstrated that EZH2 is associated with endometrial carcinoma." (PMID 25295088, 2014). "Additionally, by analyzing the correlation between EZH2 expression and clinicopathological characteristics, the expression of EZH2 was found to be associated with myometrial invasion and lymph-vascular space invasion of endometrial cancer." (PMID 25295088, 2014). "Endometrial cancer cells obtained from type II endometrial cancer showed upregulated expression of EZH2 as compared to type I endometrial cancer." (PMID 40433700, 2025).
endometrial cancer (continued). "Building on closely related endometrial cancer (EC) biology, EZH2 emerges as a druggable chromatin effector that interfaces with several of the same cascades implicated in AM." (PMID 41226749, 2025). "In the present study, we found that tumor burden was reduced in Ptend/d; Ezh2d/d mice during early tumor development, revealing an oncogenic role of EZH2 in endometrial cancer development." (PMID 35269532, 2022). "In 11 endometrial cancer cell lines and 52 clinical endometrial cancer specimens, EZH2 mRNA (RT-qPCR) was shown to be significantly overexpressed in cancer cells and tissue compared with the corresponding normal control cell lines and tissue." (PMID 36230683, 2022). "EZH2 is overexpressed in endometrial cancer, and its downregulation in endometrial cancer cells inhibits cell proliferation." (PMID 35269532, 2022). "As Ptend/d; Ezh2d/d mice showed a reduction in uterine weight compared with Ptend/d mice during early tumor development, we sought to determine the effect of Ezh2 deletion on the proliferation of endometrial cancer cells." (PMID 35269532, 2022). "Ezh2 conditional knockout mice are free of endometrial cancer but develop stratified uterine epithelia that contain basal-like cells absent in the normal uterus." (PMID 35269532, 2022). "The attenuation of early tumor growth upon Ezh2 deletion in the current study suggests a therapeutic benefit by targeting EZH2 in endometrial cancer." (PMID 35269532, 2022). "To determine the role of EZH2 in endometrial cancer development, we created mice with simultaneous deletion of Ezh2 and Pten (Ptend/d; Ezh2d/d) or Pten only (Ptend/d) in the uterus using Cre-LoxP approach." (PMID 35269532, 2022). "A more recent study has identified a correlation between overexpression of EZH2 in endometrial cancer patients and disease-free and overall survival." (PMID 35269532, 2022). "We showed that ablation of EZH2 in the PTEN-inactivated endometrium reduced tumor burden during the early pathogenesis of endometrial cancer." (PMID 35269532, 2022). "Positive correlations have been demonstrated between EZH2 protein expression and stage, grade, and depth of invasion in endometrial cancer patients." (PMID 35326450, 2022). "To assess the outcome of endometrial cancer in mice with conditional deletion of Pten and Ezh2, we generated Kaplan–Meier survival curves, which showed that Ptend/d; Ezh2d/d mice succumbed to death starting around two months of age." (PMID 35269532, 2022). "Wang and Liu concluded that autophagy in endometrial cancer cells can be prevented by miR-101-3p targeting EZH2." (PMID 34307682, 2021). "In addition, EZH2 is upregulated in endometrial cancer, and overexpression of EZH2 is significantly associated with high histologic grade, lymph node metastasis, and cervical involvement, which could serve as potential therapeutic targets for subtype II EAC patients." (PMID 34367229, 2021). "Previous studies showed that the PRC2 complex containing EZH2 plays a crucial role in endometrial cancer by promoting the proliferation, migration, and metastasis." (PMID 33728560, 2021). "A number of key factors of EMT, such as zinc finger E-box binding homeobox 2 (EZH2), Snail, N-cadherin, and E-cadherin, were modulated by miR-200 in tamoxifen-treated endometrial cancer cells." (PMID 34122542, 2021). "EZH2 has been identified as a critical PKMT that correlates with multiple adverse clinicopathologic parameters in endometrial cancer." (PMID 33050946, 2020). "Another series of 104 endometrial cancer cases revealed that higher EZH2 protein expression was independently and significantly correlated with worse progression-free survival, but not with overall survival." (PMID 33050946, 2020). "We found that EZH2 was the common transcriptional regulator of RP11-89K21.1 and RP11-357H14.17 in endometrial carcinoma with AnnoLnc, Moreover, EZH2 was positively correlated with the expression of RP11-89K21.1 and RP11-357H14.17." (PMID 32587476, 2020).
endometrial cancer (continued). "The use of GSK343 (a specific EZH2 inhibitor) was found to increase the levels of miR-361 in endometrial cancer cells." (PMID 31394811, 2019). "The expression rate of EZH2 in endometrial carcinoma tissue (68.27%) was significantly higher than that in adjacent tissue (24.03%)." (PMID 30903272, 2019). "For example, EZH2 promotes cell proliferation in laryngeal carcinoma, inducing cell metastasis in oral cancer, increasing cell invasion in endometrial cancer Dysregulation of EZH2 in HCC has been found in some studies." (PMID 30008615, 2018). "To investigate the effect of estrogen on EZH2, we evaluated the expression of Erα in the endometrial cancer cell lines we used in this project." (PMID 28418882, 2017). "To investigate the role of EZH2 in endometrial cancer, we performed knockdown experiments using siRNA against EZH2 (siEZH2#1 and #2) and control siRNA (siNC) in endometrial cancer cell lines." (PMID 28418882, 2017). "Multivariate analysis identified EZH2 expression as an independent factor for poor prognosis in endometrial cancer with endometrioid histology (HR = 5.31, 95% CI = 1.04–96.9, P = 0.0442) in the TMA data set." (PMID 28418882, 2017). "Our results indicate that EZH2 promotes the growth of endometrial cancer cells by increasing H3K27 trimethylation." (PMID 28418882, 2017). "In a quantitative real-time PCR analysis of 11 endometrial cancer cell lines and 52 clinical endometrial cancer specimens, EZH2 was significantly overexpressed in cancer cells and tissues compared to that in corresponding normal control cells and tissues." (PMID 28418882, 2017). "We found that EZH2-suppressed let 7b and miR-361, two likely tumor suppressors, inhibited endometrial cancer (EC) cell proliferation and invasion, and abrogated cancer stem cell-like properties." (PMID 28088786, 2017). "Further studies should explore the therapeutic potential of inhibiting EZH2 in patients with endometrial cancer." (PMID 28418882, 2017). "The sub-G1 population of cancer cells was significantly increased by EZH2 knockdown, indicating that EZH2 knockdown induces apoptosis in endometrial cancer cells." (PMID 28418882, 2017). "In this regard, we did not perform a functional analysis to determine the other roles of EZH2 in endometrial cancer." (PMID 28418882, 2017). "Although another study has indicated that miR-101 can suppress proliferation, migration and invasion, and stem cell-like phenotype of aggressive endometrial cancer cells, at least through targeting EZH2, MCL-1 and FOS." (PMID 29333128, 2017). "Previous studies have shown that EZH2 knockdown decreases proliferation in endometrial cancer cells." (PMID 28418882, 2017). "Treatment with the EZH2 inhibitor GSK126 suppressed the growth of endometrial cancer cell lines, with an increasing effect observed at increasing concentrations (IC50: 2.37–5.07 μM) and reduced H3K27 me3 levels." (PMID 28418882, 2017). "EZH2 expression was significantly higher in the 52 endometrial cancer tissues than in the four normal control tissues." (PMID 28418882, 2017). "Our study suggests that high EZH2 expression is a significant prognostic factor in endometrial cancer, according to the TCGA and TMA data." (PMID 28418882, 2017). "Further, we confirmed that EZH2 knockdown suppresses the growth of endometrial cancer cells and induces apoptosis." (PMID 28418882, 2017). "We therefore investigated the involvement of EZH2 in endometrial cancer and evaluated its therapeutic potential." (PMID 28418882, 2017). "Significant growth suppression was detected in the four endometrial cancer cell lines after EZH2 knockdown." (PMID 28418882, 2017). "In the present study, the expression of EZH2 in endometrial cancer and precancerous lesions was evaluated, and the potential role of EZH2 in endometrial cancer cell proliferation was further investigated." (PMID 25295088, 2014).
endometrial cancer (continued). "This indicates that endometrial cancers with high expression levels of EZH2 tend to be more invasive." (PMID 25295088, 2014). "EZH2 starts to become expressed in the precursor lesions of endometrial cancer, which indicates that high EZH2 expression is an early event of endometrial cancer carcinogenesis." (PMID 25295088, 2014). "Reduced cell proliferation was identified after EZH2 was silenced by siRNA, indicating that EZH2 was involved in the cell proliferation of endometrial cancer." (PMID 25295088, 2014). "Overexpression of EZH2 was observed in the epithelium of endometrial cancer, atypical hyperplasia and complex hyperplasia compared with the expression in simple hyperplasia and normal endometrium." (PMID 25295088, 2014). "One of these approaches targeted the enhancer of zeste homolog 2 (EZH2) due to its high expression in breast, prostate, and endometrial cancers." (PMID 24244833, 2013). "Also, genes (Nanog, ALDH, EZH2) related to stemness and aberrant transcriptome were found to be upregulated in type II endometrial cancer." (PMID 40433700, 2025). "lncRNA nuclear-enriched abundant transcript 1 could up-regulate the expression of EZH2 by targeting miR-144–3p, promoting the function of EZH2 in the progression of endometrial cancer." (PMID 40028035, 2025). "The enhancer of zeste homolog 2 (EZH2) is also contributed and studied in endometrial cancer." (PMID 39188680, 2024). "A recent study demonstrated that miR-101-3p prevented retinoblastoma cell proliferation by targeting EZH2 and HDAC9, prevented autophagy in endometrial cancer cells by targeting EZH2 and inhibits invasion and metastasis in renal cell carcinoma by Targeting EZH2." (PMID 36873948, 2023). "This may offer new opportunities for endometrial cancer treatment with the assessment of EZH2 inhibitors or ATR inhibitors in the setting of recurrent uterine CCC." (PMID 37353806, 2023). "The current study revealed dual roles of EZH2 in endometrial cancer development." (PMID 35269532, 2022). "EZH2 is overexpressed in both human endometrial cancer cell lines and endometrial cancer tissues." (PMID 35269532, 2022). "Current results revealed dual roles of EZH2 in the development of endometrial cancer lacking Pten, a gene frequently mutated in endometrioid carcinomas." (PMID 35269532, 2022). "However, it appears that microRNA-361/Twist axis plays an important role in mediating the role of EZH2 in driving endometrial cancer development." (PMID 35269532, 2022). "Additionally, the histone methyltransferase EZH2 was overexpressed in endometrial cancer cells, and knockdown of EZH2 expression as well as treatment with an EZH2-selective inhibitor resulted in cancer growth suppression and apoptosis." (PMID 36358786, 2022). "Both PTEN and EZH2 play important roles in endometrial cancer." (PMID 35269532, 2022). "Our results revealed dual roles of EZH2 in endometrial cancer development." (PMID 35269532, 2022). "EZH2 silencing promoted autophagy in endometrial cancer cells." (PMID 34790699, 2021). "Additionally, YY1 was shown to silence APC gene expression in endometrial cancer cells by enhancing EZH2-mediated H3K27me3 deposition on the APC promoter." (PMID 33728560, 2021). "EZH2 was also verified as a direct target of miR-200 in endometrial cancer cells." (PMID 34122542, 2021). "Finally, we also show that a selective EZH2 inhibitor suppresses the growth of endometrial cancer cells." (PMID 28418882, 2017). "In addition, we showed via quantitative real-time PCR that EZH2 is significantly overexpressed in 11 endometrial cancer cell lines and clinical samples compared with that in normal samples." (PMID 28418882, 2017). "EZH2 targets genes which may exhibit modified function in endometrial cancer including: p16, E-cadherin, SFRP1, DKK3, and β-catenin." (PMID 29093822, 2017).
endometrial cancer (continued). "In addition, knockdown of EZH2 using specific siRNAs resulted in growth suppression and apoptosis induction of endometrial cancer cells, accompanied by attenuation of H3K27 trimethylation." (PMID 28418882, 2017). "Hence, in the present study, we investigated the expression and function of EZH2 in endometrial cancer." (PMID 28418882, 2017). "In conclusion, the present findings highlight that EZH2 overexpression is involved in endometrial cancer, and that EZH2 might be a promising candidate for treating endometrial cancer." (PMID 28418882, 2017). "The biological function of EZH2 in endometrial cancer was further evaluated." (PMID 25295088, 2014). "Cell growth was inhibited after EZH2 knockdown in endometrial cancer cells." (PMID 25295088, 2014). "Furthermore, high EZH2 expression also presented in the majority of atypical hyperplasia and endometrial cancer samples." (PMID 25295088, 2014). "Furthermore, small interfering RNA was utilized to investigate the role of EZH2 in endometrial carcinoma cell proliferation, and the results showed that EZH2 knockdown suppressed the proliferation of endometrial carcinoma cells in vitro." (PMID 25295088, 2014). "Hence, these results reveal dual roles of EZH2 in endometrial cancer development." (PMID 35269532, 2022). "However, the role of EZH2 in endometrial cancer remains poorly defined." (PMID 35269532, 2022). "Mono-chemotherapy of a selective EZH2 inhibitor such as GSK126, or combination chemotherapy using a selective EZH2 inhibitor and one or more conventional anticancer drugs, might be an appropriate strategy to cure high-risk endometrial cancer." (PMID 28418882, 2017). "EZH2 expression correlated with high tumor grade, deep myometrial invasion, lymphovascular space invasion and enhanced cellular proliferation, as well as decreased overall survival, suggesting a role as both a prognostic and therapeutic marker in endometrial cancer." (PMID 29093822, 2017). "Therefore, a correlation between EZH2 expression and estrogen may exist in ERα-positive endometrial cancer cell lines." (PMID 28418882, 2017). "However, the physiological importance of EZH2 and its clinical relevance in endometrial cancer remain unclear." (PMID 28418882, 2017). "However, this is the first report of the effectiveness of EZH2 inhibition in endometrial cancer." (PMID 28418882, 2017). "Thus, EZH2 knockdown suppresses endometrial cancer cell growth and induces apoptosis." (PMID 28418882, 2017). "For example, Lnc-DLEU2 can drive epithelial-mesenchymal transition and glycolysis in endometrial cancer through HK2 by competitively binding to miR-455 and by modulating the enhancer of zeste 2 polycomb repressive complex 2 subunit (EZH2)/miR-181 pathway." (PMID 35156508, 2022). "YY1 is required to promote the recruitment of EZH2 to the miRNA-361 promoter, suggesting that YY1 governs the CSC phenotype in endometrial cancer." (PMID 33728560, 2021). "Evidence has shown that miR-144 targets 3′UTR of Enhancer of zeste homolog 2 (EZH2), a transcriptional repressor, suppresses the expression of EZH2 and inhibits proliferation, migration and invasion in human endometrial cancer cell lines." (PMID 33849540, 2021). "In this study, we demonstrated that TCF3 is epigenetically silenced by EZH2 and DNMT3B and functions as a tumor suppressor in endometrial cancer." (PMID 34175897, 2021). "In this study, EZH2 knockdown decreased cell proliferation and induced apoptosis by decreasing the H3K27 me3 level in endometrial cancer cell lines." (PMID 28418882, 2017). "The clinical significance of EZH2 inhibitors such as GSK126 in the treatment of various types of cancer, including endometrial cancer, should be explored further in future studies." (PMID 28418882, 2017). "In conclusion, overexpression of EZH2 correlates with deep myometrial invasion, LVSI and enhanced cell proliferation of endometrial cancer cells." (PMID 25295088, 2014).